MAPK3 (mitogen-activated protein kinase 3)
Diseases named in the same sentence as MAPK3 in open-access papers (continued):
Sharing a sentence is not in itself a finding about the gene and the disease.
tumor (2,199 papers, 1999 to 2026). "PRKACB (HR = 0.586), PPP2R5C (HR = 0.388), and MAPK3 (HR = 0.143) are associated with improved survival, suggesting their higher expression is protective against tumor progression." (PMID 39975150, 2025). "Phosphorylated AMPK expression was associated with p-MAPK3/1 expression (P<0.0001) and inversely with high tumour grade (P=0.0009), MSI-high (P=0.0021) and CIMP-high (P<0.0001)." (PMID 20808308, 2010). "Among the nine other main spleen proteins concerned with a complete reversion of the increase produced by tumor progression, we found two proteins involved in cell transduction pathways, one located in the cytosol (encoded by Prkar1a), and the second in the nucleus (encoded by Mapk3)." (PMID 34445271, 2021). "The H/L patients exhibited higher frequencies of NF1, CBL, MAPK3, and BMPR1A mutations, underscoring the need for further research into their functional roles in tumor progression." (PMID 40282501, 2025). "Subsequently, we conducted signaling pathway clustering on the altered genes enriched in the MAPK pathway and identified MAPK3 as a key regulator of the tumor cell changes." (PMID 38907234, 2024). "MK03 (mitogen-activated protein kinase 3) is targeted by multiple extracellular signal–regulated kinase 1/2 (ERK1/2) kinase inhibitors for the treatment of neoplasms." (PMID 37126556, 2023). "MAPK3 was weakly positive in most normal renal tissues according to CAB002683 staining but moderately positive in most tumor tissues." (PMID 37056387, 2023). "By a-CGH analysis on tumor DNA at progression, we found the loss 12p13.31, containing KLRB1 gene, the loss 16p11.2 containing MAPK3 gene, and the loss 16q11.2–q24.3, containing FANCA gene." (PMID 35742955, 2022). "MAPK3 is related to tumor cell development, differentiation, apoptosis, angiogenesis, invasion and metastasis." (PMID 35672352, 2022). "Aberrant expression of MAPK3 is related to invasion, metastasis and drug resistance of various tumour cells." (PMID 34809653, 2021). "The abnormal expression of MAPK3 was related to the invasion, metastasis, and drug resistance of a variety of tumor cells." (PMID 33953786, 2021). "As a member of the mitogen-activated protein kinase (MAPK) family, the abnormal expression of MAPK3 is related to the invasion and metastasis of various tumor cells." (PMID 34335829, 2021). "Additional studies are needed to confirm our findings and elucidate the exact mechanism of effect of MAPK3/1 on AMPK to modify tumour behaviour." (PMID 20808308, 2010). "Additional studies are necessary to confirm our observations and to elucidate exact mechanisms by which AMPK and MAPK3/1 interact and affect tumour behaviour." (PMID 20808308, 2010). "Furthermore, gene set enrichment analysis (GSEA) showed that USP7 knockdown is significantly associated with the inhibition of tumor formation by downregulating the genes related to MYC and MAPK3 pathways." (PMID 39840939, 2025). "Then we further analyzed the differences in tumor-infiltrating immune cells between the MAPK3 high expression group and the low expression group, and found that there were significant differences in the expression of aDC, macrophages, and Tgd between the two groups." (PMID 38800011, 2024). "Also among our findings, we identified the pathway “MAPK/MAPK3 signaling”, which is involved in promoting cell survival and chemotherapy response by the tumor." (PMID 39001535, 2024). "A previous study revealed that phosphorylated AMP-activated protein kinase (AMPK) expression in CRC was associated with superior prognosis among p-MAPK3 positive cases, indicating a possible interaction between the AMPK and MAPK pathways influencing tumor behavior." (PMID 33743701, 2021). "MAPK3/1 (ERK1/2) plays a key role in tumour growth by regulating cell cycle progression." (PMID 34954904, 2021). "MAPK1 and MAPK3 were considered as key proteins with highest scores of centrality indices, which might play an important role in the anti-tumor effect of the essential oil." (PMID 29282071, 2017).
tumor (continued). "Given potential roles of AMPK as a regulator of cellular metabolism and a tumour suppressor related to cellular signaling pathways (e.g., the MAPK3/1 pathway), we hypothesised that AMPK might interact with MAPK3/1 to modify tumour behaviour." (PMID 20808308, 2010). "Considering a pivotal role of AMPK as a regulator of cellular metabolism and the relationship of AMPK with the MAPK3/1 (ERK1/2) pathway and other signaling pathways, we hypothesised that cellular AMPK might interact with MAPK3/1 to modify tumour behaviour." (PMID 20808308, 2010). "Our findings may support the hypothesis that AMPK activation can make a strong impact on tumour behaviour as the ‘brake’ only when MAPK3/1 is active." (PMID 20808308, 2010). "Several whole-transcriptome chips and subsequent tissue microarray analyses have demonstrated that the MAPK3 signaling pathway is associated with lymph node metastasis in OSCC, while high levels of MAPK-related proteins were associated with advanced tumor stage and lymph node metastasis." (PMID 38539520, 2024). "Interestingly, no changes in the phosphorylation of the IGF1-dependent signal transducer AKT (also known as Akt1), as well as of ERK1/2 (Mapk3/Mapk1) and p38 (Ahsa1) were observed in the skeletal muscle of tumor-bearing animals relative to the respective controls." (PMID 31915140, 2020). "Oxidative phosphorylation components (NDFs, COXs, TCIRG1, LHPP) and chemical carcinogenesis pathways involving reactive oxygen species (CYP1B1, GSTs, AKT2, IKBKB, MAPK3, MAP2K2) exacerbate DNA damage and promote tumour aggressiveness." (PMID 41007296, 2025). "MAPK3, also known as extracellular signal-regulated kinase 1 (ERK1), is located downstream of the Raf/MEK/ERK pathway and regulates cell proliferation, differentiation, and survival, amplifying signals during tumor invasion and metastasis." (PMID 39346898, 2024). "Thus, we hypothesized that MAPK3 may regulate tumor apoptosis and autophagy by affecting BAX." (PMID 38800011, 2024). "For liver tissue, relative to SKBR3 bearing tumor control, BPAF at 20 mg/kg bw/day significantly up-regulated the gene expression of four genes (MAPK3, MAPK6, EBP1, CCND1), whereas the mRNA relative levels of the other 15 genes had no a statistical difference." (PMID 36497816, 2022). "Our study evaluated the correlation between MAPK3, CD44, and tumor-infiltrating immune cells in the AML microenvironment by applying the “GSVA” package." (PMID 36612069, 2022). "Baseline PDX derived from P360 (BTY06) had overall low pTyr levels compared to the recurrent tumor (BTY29) that exhibited high phosphorylation of central regulator nodes, such as PIK3R1, STAT3, MAPK1, and MAPK3." (PMID 36077757, 2022). "Several key downstream regulators of PTEN/Akt signalling, such as GSK3, CHK1, MAPK3, FOXO, were critical for tumour cell growth and survival." (PMID 34416907, 2021). "Conversely, KLF4, CXCL2, MAPK3 and TIMP4 were up regulated in normal samples compared to tumor tissues." (PMID 26498364, 2015). "Additional repressed genes were ANGPTL2, TGM2, IL-6, CSF1R, TNFSF12 as well as a key regulatory MAP kinase ERK1/2 (MAPK3), all known to stimulate chronic inflammatory signaling in the tumor microenvironment and to promote cancer metastasis." (PMID 24498382, 2014). "MAPK3, as a critical component involved in the MAPK/ERK cascade pathway, and inhibition of MAPK3 can significantly inhibit cancer-stroma interactions and tumor metastasis." (PMID 40351428, 2025). "We speculate that CSS may regulate the activity of immune‐related factors in the tumour microenvironment, reverse immune escape, enhance immune responses through AKT1, MAPK3, and CASP3, and synergistically alleviate HCC." (PMID 38613352, 2024).
tumor (continued). "In conclusion, CSS may regulate the activity of immune‐related factors in the tumour microenvironment, reverse immune escape, enhance immune responses through AKT1, MAPK3, and CASP3, and synergistically alleviate HCC." (PMID 38613352, 2024). "The heightened activity of MAPK3 in TNBC may drive the rapid growth and survival of tumor cells, particularly in environments with limited resources or high stress." (PMID 39850811, 2024). "MAPK1 (ERK2) and MAPK3 (ERK1) are key nodes of biochemical signals in biology, especially the RAF/MEK/ERK axis, which has an important effect on malignant transformation and drug resistance of tumor cells." (PMID 38200039, 2024). "However, this comparison allowed us to identify kinases, which show higher differential regulation in tumours than acute perturbation such as PRKACA, MAPK1 and MAPK3." (PMID 36688815, 2023). "Importantly, EGFR, MET, EPHA2, MAPK1, MAPK3, and RPS6 kinase pathways were strongly dependent on FLCN in RPTEC and also strongly respond to FLCN reconstitution in this BHD tumor cell line, as highlighted in the UOK257 INKA rankings in orange." (PMID 35863698, 2022). "Isorhamnetin, kaempferol, FA, calycosin, hederagenin might play an anti-tumor role through targeting AKT1, CDK1 TYMS, MAPK3, AR, respectively." (PMID 34955857, 2021). "Indeed, significant down-regulation of MAPK3, MAP2K2, MAPKAPK3, ELK1 and up-regulation of the phosphatase DUSP1 was found in the reprogrammed tumours." (PMID 29662623, 2018). "Similarly to MAPK3, MAP2K1 (MEK1) mediates FGF-stimulated endothelial-cell proliferation in tumor models." (PMID 22355249, 2012). "While the roles of canonical MAPKs, such as MAPK3/1 [extracellular signal–regulated kinase 1/2 (ERK1/2)], MAPK11-14 (p38β/γ/δ/α), and MAPK8-10 (c-Jun N-terminal kinase 1/2/3), are well established in carcinogenesis and tumor progression, the role of MAPK6 in human cancers remains unclear." (PMID 34767444, 2021). "Conversely, proteins hypophosphorylated (Tumor/Normal phosphorylation spectral count ratio >1) in tumors include the transcription factors STAT1 and STAT5, the protein tyrosine phosphatase PTPN11, the G-protein coupled receptor GPRC5A, and the kinases MAPK1, MAPK3, and TNK2." (PMID 19946374, 2009). "Inhibition of STAT3 and EGR1, but not MAPK3 and EGR2, significantly abrogated the capacity of tumor cells to form cell-in-cell structures upon incubation with IFNγ-stimulated T cells and with T cell secreted granules." (PMID 36124553, 2022).
cancer (1,821 papers, 2002 to 2026). A tumor composed of atypical neoplastic, often pleomorphic cells that invade other tissues. "This showed that MAPK3 expression was connected to the infiltration of activated mast cells, B cells, macrophages, and fibroblasts associated with cancer." (PMID 38800011, 2024). "In this study we selected from COSMIC database a set of MAPK1 and MAPK3 somatic variants found in cancer tissues carrying missense mutations distributed all over the MAPK1 and MAPK3 sequences." (PMID 37891694, 2023). "COSMIC database reports many somatic missense variants of MAPK1 and MAPK3, found in cancer tissues, carrying single mutations in different regions of the sequence." (PMID 37891694, 2023). "Many somatic missense variants of MAPK1 and MAPK3, found in cancer tissues, are reported in COSMIC database each carrying single mutations in different regions of the sequence." (PMID 37891694, 2023). "Using whole-exome sequencing, five single nucleotide polymorphisms within mitogen-activated protein kinase 3 (MAP2K3) were identified in an ALL cancer patient library from the U.S./Mexico border." (PMID 34830095, 2021). "cBioPortal was used to investigate the genomic changes of three Nitroglycerin genes (EGFR, HRAS and MAPK3) associated with respective cancers." (PMID 34764329, 2021). "In addition, the expression of MAPK3 was significantly positively correlated with the infiltration levels of macrophages, B cells, mast cell activation, and cancer-associated fibroblasts." (PMID 38800011, 2024). "Mutation of proteins in one gene MAPK3 was found to be unique to each type of cancer." (PMID 34764329, 2021). "Therefore, the CBL and MAPK3 changes observed in this study may reflect a rebalancing of EGFR signaling that can lead to inhibition of cancer cell growth, even in the presence of KRAS mutations." (PMID 41226554, 2025). "Alterations in CBL and MAPK3 reflect a balance of signaling pathways involved in cancer cell growth and survival, particularly the EGFR/MAPK pathway, which plays a key role in stimulating cell proliferation, evading apoptosis, and metastasis." (PMID 41226554, 2025). "MAPK3 regulates processes such as cell proliferation, survival, and differentiation, which are often dysregulated in aggressive cancers." (PMID 39850811, 2024). "The present study performed molecular docking and dynamics simulation to identify potential MAPK3 inhibitors from natural flavonoids, possibly leading to drug development in cancer therapy." (PMID 37090055, 2023). "MAPK1 and MAPK3 are the components of the rout that orchestrate the rapid cancer cell division and determine the aggressive cancer cells behavior." (PMID 36980957, 2023). "MAPK3, MAPK1, and EGFR were ranked among the top 3 target proteins, and were also the key proteins tightly associated with cancer." (PMID 38143380, 2023). "The abnormal expression of targets (IL6, MAPK1, PPARG, PTGS2, and MAPK3) leads to cell proliferation and a variety of cancer types." (PMID 35992697, 2022). "The role of AL512274.1 in cancer is still unclear, but studies have found that its co-expressed mRNA (MAPK3) is involved in the control of cell proliferation, differentiation and autophagy." (PMID 35299954, 2022). "Experiments have shown that MAPKl4 and MAPK3/1 pathways have the function of controlling the migration and proliferation of malignant tumors." (PMID 35321506, 2022). "The following figure shows the Alteration frequency type of EGFR, HRAS and MAPK3 in four types of cancer." (PMID 34764329, 2021). "The expression of MAPK3 was significantly higher (P < 0.05) in HR + HER2− cancer tissue than in para-carcinoma tissue or benign tumor tissue when assessed by 5 or 3 multi-gene RG combinations." (PMID 34895237, 2021).
cancer (continued). "MAPK3 is a kinase that has various biological functions, including promoting cell growth, cell proliferation, and cell cycle progression in a variety of cancers." (PMID 33001583, 2020). "Both genes (Sha-miR-71a and MAPK-3) were found to be significantly expressed in cancer cases more than benign cystitis cases." (PMID 33139749, 2020). "It is reported that PLC patients with high phosphorylated MAPK3 (also called ERK1) had significantly higher cancer recurrence and worse OS, and the impact of MAPK3 on survival was also verified by the survival curve in this study." (PMID 32382293, 2020). "Other notable hub genes have also been claimed to be associated with cancers, including MAPK1, MAPK3, JAK2, EGFR, KRAS and NRAS." (PMID 27467251, 2016). "Both the SCP2 and BSG branches share the same CAV1 upstream regulators such as MAPK3, TNFRSF1B, and GNAI2, which have been implicated in cancer cells death pathways." (PMID 24949431, 2014). "Notably, the protein targets such as epidermal growth factor receptor (EGFR), mitogen-activated protein kinase 1 (MAPK1) and mitogen-activated protein kinase 3 (MAPK3) were found to maximally participate in >10 cancer pathways." (PMID 40028476, 2025). "C, but no pathways were significantly enriched in Res Cl B. MAPK1 and MAPK3 signaling is known to affect cancer cell migration and metastasis, while Rho GTPases also affect cell motility, which may also not be directly linked to Olaparib resistance." (PMID 40669753, 2025). "Due to the critical role of MMP8 and MAPK3 in cancer development and metastasis, kaempferol and its glycosylated forms could be considered drug candidates for cancer therapy." (PMID 37090055, 2023). "Interestingly, several multi-omics analyses prove that MAPK3 occupies one of the top networking protein positions along with EGFR in various cancers, resulting in poor prognosis." (PMID 38067326, 2023). "Indeed, MTOR and MAPK3/1 pathways, among other important cellular processes, can positively regulate protein synthesis, which is required to sustain cancer cell survival and proliferation." (PMID 37511362, 2023). "Negative regulation of MAPK3 expression using miRNAs has led to therapeutic effects in cancer." (PMID 37090055, 2023). "Some studies have suggested that the AMPK and MAPK3/1 pathways may be biological indicators and possible targets for cancer therapy based on metabolic changes." (PMID 36276869, 2022). "Furthermore, considering hallmark types and numbers, MAPK3 and NRAS showed the same profile, and they were involved in 9 out of 10 cancer hallmarks." (PMID 36304266, 2022). "Moreover, the pathway genes with most links to the query set: MAPK1, MAP2K1, YWHAB, MAP2K2 and MAPK3 are known to be highly expressed in various sorts of cancer, which further highlights the connection to this cancer-derived query set." (PMID 35266519, 2022). "Moreover, we observed phase-shifted transcript pairs related to cancer hallmark genes like CASP8 and Mitogen Activated Protein Kinase 3 (MAPK3) that were unique to HCT116_NR1D1KO." (PMID 35552415, 2022). "After further topological analysis by Network Analyzer, we found that NR may play a co-regulatory role on ASD mediated by AKT1, MAPK1, MAPK3 and involve the proteoglycan pathway in cancer, thyroid hormone signaling pathway, ROS pathway, and other pathways." (PMID 36401485, 2022). "Furthermore, the compounds-targets docking analysis results also demonstrated that there was good affinity between MAPK3 and several compounds of GEB including koumine, confirming the role of MAPK3 as one of the key targets in the anti-cancer effect of GEB." (PMID 33743701, 2021).